TFF1 (trefoil factor 1)
Diseases named in the same sentence as TFF1 in open-access papers (continued):
Sharing a sentence is not in itself a finding about the gene and the disease.
nephrolithiasis (4 papers, 2013 to 2022). The presence of a calculus in the pelvis of the kidney; this is most often composed of mineral salts and proteins. "In this study, the discovery set including 230 cases and 250 controls was used to analyze the association between seven tagSNPs of TFF1 gene and the nephrolithiasis risk." (PMID 35987613, 2022). "In this study, we selected seven tagSNPs of TFF1 and assessed their association with nephrolithiasis risk by using a two-stage case–control study, followed by molecular biological experiments." (PMID 35987613, 2022). "To date, few studies were taken to prove the association between the TFF1 polymorphisms and nephrolithiasis risk." (PMID 35987613, 2022). "An obvious increase in nephrolithiasis risk existed with the interaction between polymorphisms of TFF1 and drinking status (Pinteraction = 0.037)." (PMID 35987613, 2022). "In summary, our study provided evidence that the TFF1 promoter activity reduced by rs3761376 A allele could at least partially lead to the decreased TFF1 expression and ultimately increase the risk of kidney stones." (PMID 35987613, 2022). "Therefore, to verify the association between the TFF1 genetics and nephrolithiasis risk in terms of mechanism, we need do more well-designed functional study." (PMID 35987613, 2022). "It suggests that the low expression of TFF1 at the kidney may lead to the increase of CaOx crystals, contributing to the increased risk of nephrolithiasis." (PMID 35987613, 2022). "Other results of the stratified analysis indicate that the influence of genetic variants in TFF1 on the risk of nephrolithiasis may be regulated by specific demographic factors and environmental exposures." (PMID 35987613, 2022). "For further study of the rs3761376 effects, we evaluated the expression levels of TFF1 with known genotypes in 52 kidney tissues of nephrolithiasis patients." (PMID 35987613, 2022). "TFF1 is a novel and potent CaOx crystal growth inhibitor with a potential pathophysiological role in nephrolithiasis." (PMID 24282531, 2013). "Moreover, by evaluating the expression levels of TFF1 with known genotypes in 52 kidney tissues of nephrolithiasis patients, a significantly lower TFF1 expression was found along with the increase of the rs3761376 A allele." (PMID 35987613, 2022). "As a novel potent CaOx crystal growth inhibitor, TFF1 may play a potential pathophysiological role in nephrolithiasis." (PMID 35987613, 2022). "Trefoil Factor 1 (TFF1) is considered to be able to inhibit the formation of kidney stone." (PMID 35987613, 2022). "Besides, another study indicated that TFF1 is a new and potent CaOx crystal growth inhibitor with potential pathophysiological effects in kidney stones, consistent with previous experiments." (PMID 35987613, 2022). "However, the mechanism of regulating TFF1 expression and its role in kidney stones still needs further investigations." (PMID 35987613, 2022). "However, genetic variants in TFF1 and corresponding function in kidney stone development are still not well studied." (PMID 35987613, 2022). "However, to date, there is no studies to evaluate the association between the TFF1 polymorphisms and nephrolithiasis risk." (PMID 35987613, 2022). "However, blockade of both N-part and C-part of TFF1 molecule with neutralizing antibodies did decreased the ability of TFF1 to inhibit the growth of kidney stones, and the C-terminus seems particularly important in the inhibition of oxalate crystal growth by TFF1." (PMID 30042499, 2019). "However, the various relevant clinical biochemical characteristics were not collected in our study, and it is unclear whether the association of TFF1 tagSNPs with nephrolithiasis is independent of these factors." (PMID 35987613, 2022). "In the human urinary tract, TFF3 is detected as the most abundant form followed by TFF1, while urine TFF2 and TFF3 are increased in patients with nephrolithiasis." (PMID 29850501, 2018).
oral mucositis (4 papers, 2017 to 2021). Inflammation of the mucous membranes of any of the structures in the mouth. "Currently, a study designed recombinant strains of L. lactis to produce Trefoil factor 1 (TFF-1), involved in the maintenance of epithelial barrier integrity, revealing promising outcomes in the treatment of oral mucositis patients in clinical trials." (PMID 30305667, 2018). "For example, it would be promising to study whether synthetic peptides mimicking the C-terminal region of TFF1 are able to reduce oral mucositis." (PMID 32260357, 2020). "Moreover, a recombinant Lactococcus lactis strain, genetically modified to secrete human TFF1, was able to reduce the severity of mucosal damage in an animal model of oral mucositis." (PMID 28210256, 2017). "Salivary TFF1 and TFF3 concentrations are reduced in patients with chronic periodontitis, whereas salivary TFF3 is elevated in children with oral mucositis." (PMID 34830103, 2021). "Later, a mouth rinse formulation of L. lactis-secreting TFF1, coded AG013, was applied to reduce radiation-induced oral mucositis in a hamster model." (PMID 34830103, 2021).
bone metastasis (3 papers, 2018 to 2025). Transfer of a neoplasm from its primary site to bones. "And the identification of high trefoil factor 1(TFF1) expression in CTCs as a key feature of bone metastasis has been reported." (PMID 41372129, 2025). "The high level of TFF1 mRNA was related to the site of metastasis to show that 77.8% of cases had bone metastasis, while 75% of cases with high TFF3 mRNA level showed lymph node involvement and 68.8% showed lung metastasis." (PMID 29977293, 2018).
Crohn disease (3 papers, 2013 to 2022). A gastrointestinal disorder characterized by chronic inflammation involving all layers of the intestinal wall, noncaseating granulomas affecting the intestinal wall and regional lymph nodes, and transmural fibrosis. "For example, TFF1 synthesis is induced in mucosal ulcerations during Crohn’s disease, and cerebral TFF1 expression is increased in two murine models of neuroinflammation." (PMID 35628183, 2022). "Immunohistochemical analysis of trefoil factor TFF1, 2 and 3 showed that TFF1 and 3 localized to goblet cells in both normal colon tissue and in tissue from patients with ulcerative colitis or Crohn’s disease." (PMID 23691218, 2013).
esophageal adenocarcinoma (3 papers, 2017 to 2025). A malignant tumor with glandular differentiation arising predominantly from Barrett mucosa in the lower third of the esophagus. "This suggests that TFF1 expression might be induced in response to the injury caused by the acid reflux, which is associated with Barrett’s esophagus, but ceases during the progression to EAC." (PMID 29296124, 2017). "Interestingly, previous studies have shown TFF1 upregulation in Barrett’s esophagus, a premalignant condition which increases the risk of esophageal adenocarcinoma development." (PMID 29296124, 2017). "Finally, using TCGA data we showed that TFF1 loss is observed in ESCC, but not in esophageal adenocarcinoma, highlighting the different molecular mechanisms involved in the development of each histological subtype of esophageal cancer." (PMID 29296124, 2017).
Helicobacter infection (3 papers, 2017 to 2022). "Since TFF1 expression is reduced during chronic Helicobacter infection with a loss of gastric mucosa protection, we investigated the molecular pathways involved in this reduction." (PMID 36514982, 2022). "Our results show that TFF1 expression is induced in infected cells; in addition, the inflammatory response upon Helicobacter infection is inversely associated to pre-existing TFF1 protein levels." (PMID 29085807, 2017). "In vitro studies of TFF1 expression upon Helicobacter infection always reveal an upregulation of the gastrointestinal protein." (PMID 36514982, 2022). "The use of the mucosoid cellular system revealed that TFF1 is more expressed in foveolar than in basal glands and correlates with a reduced inflammatory response measured in these cells upon Helicobacter infection." (PMID 36514982, 2022). "We recently demonstrated that TFF1 expression is differently regulated in a mouse model of Helicobacter infection." (PMID 33673347, 2021). "The over-expression of TFF1 during the acute phase is in agreement with cellular studies that report induction of TFF1 upon Helicobacter infection." (PMID 33673347, 2021). "Taken together, these data suggest that TFF1 is induced upon Helicobacter infection in both cellular systems, while TFF2 and TFF3 responses change depending on the host system." (PMID 29085807, 2017). "In this paper we characterized TFFs expression, with particular attention to TFF1, under Helicobacter infection in gastric cell lines." (PMID 29085807, 2017). "Here, to investigate TFFs expression, with particular attention to TFF1, under Helicobacter infection, we started using different cancer cells with different basal levels of TFF1." (PMID 29085807, 2017). "A mouse model was used to distinguish TFF1 mRNA expression between acute and chronic stages of Helicobacter infection." (PMID 29085807, 2017). "In this paper we characterized TFFs expression, with particular attention to TFF1, under Helicobacter infection in gastric cell models and in mice antrum." (PMID 29085807, 2017). "Moreover, in copper-deprivation conditions, bacteria hardly colonize the epithelium, and inflammation is reduced, and this correlates with higher TFF1 levels, confirming its protective role during Helicobacter infection." (PMID 36514982, 2022). "However, our cellular data on TFF1 up-regulation upon Helicobacter infection, seem in contrast to in vivo analyses where it is down regulated." (PMID 29085807, 2017). "TFF1, a mucin-associated secreted peptide of gastric mucous cells, is known as a protective agent for stomach epithelium under different stimuli, but its role upon Helicobacter infection is still not clear." (PMID 29085807, 2017). "In conclusion, in this study we demonstrated that TFF1 is up-regulated during acute Helicobacter infection and inversely correlated to inflammatory response, suggesting that it could help cells to counteract bacteria and the development of a chronic inflammation." (PMID 29085807, 2017).
mucositis (3 papers, 2017 to 2020). Mucositis is inflammation and damage of the mucous membranes lining the mouth and other parts of the gastrointestinal (GI) tract. "This could open new clinical perspectives because TFF1 has therapeutic potential, e.g., for reducing mucositis in patients receiving chemotherapy." (PMID 32260357, 2020). "This could open interesting clinical perspectives because TFF1 has therapeutic potential, e.g., by reducing mucositis in cancer patients receiving chemotherapy." (PMID 31801293, 2019). "In fact, recent studies have designed recombinant strains of L. lactis to produce anti-inflammatory proteins, involved in the maintenance of epithelial barrier integrity, such as Trefoil factor 1 (TFF-1), which has been promising to treat mucositis in clinical trial as well." (PMID 28193209, 2017).
bladder cancer (2 papers, 2021 to 2022). "Several of the individual genes upregulated by Gardnerella exposures are involved in epithelial to mesenchymal transition (Cxcl5, Cxcr2, Tff1) or known to be elevated during squamous metaplasia or bladder cancer (Anxa10, Fosl1, Krt6a, Mmp10)." (PMID 35782131, 2022).
chronic gastritis (2 papers, 2018 to 2022). Inflammation of the stomach that is chronic in nature. "We decided to analyse the molecular events that occur during chronic gastritis and predispose to the appearance of malignant lesions, such as the silencing of TFF1, which is one of the gastric-tumour suppressors." (PMID 36514982, 2022). "Based on gene expression quantity, TFF1 and EGR1 can be introduced as the most critical genes related to chronic gastritis." (PMID 30425814, 2018).
chronic kidney disease (2 papers, 2015 to 2017). Impairment of the renal function secondary to chronic kidney damage persisting for three or more months. "In chronic kidney disease (CKD), TFF1 and TFF2 are reported to be upregulated." (PMID 28355260, 2017).
clear cell carcinoma (2 papers, 2022 to 2023). "The diagnostic value of TFF1, TFF2 and TFF3 was then evaluated by immunohistochemistry on 206 stage I-II OCs stratified by histotype (high-grade serous carcinoma [HGSC], endometrioid carcinoma [EC], clear cell carcinoma [CCC], and MC)." (PMID 36818673, 2022).
colon adenoma (2 papers, 2016 to 2024). An adenoma that arises from the colon. "Earlier studies confirmed TFF1 expression in colon adenomas and also reported TFF1 staining from other preneoplastic lesions, including, for example, intestinal metaplasia." (PMID 39410561, 2024). "Forced expression of TFF1 in colonic adenoma cells provokes anchorage-independent growth and increased growth of xenografts." (PMID 28430953, 2016). "The increase in TFF1 staining that was seen in colon adenomas as compared to normal colon mucosa further supports this notion." (PMID 39410561, 2024).
helminth infection (2 papers, 2020 to 2024). "It is possible that the upregulation of TFF1 in a helminth infection is to assist with the healing of damaged mucosa caused by the invading helminth and the hosts’ immune response against the helminth." (PMID 39596084, 2024).
Obesity (2 papers, 2020 to 2021). Accumulation of substantial excess body fat. "On the other hand, prostaglandin-endoperoxide synthase 2 (PTGS2), cyclin D1 (CCND1), and TFF1 (an ESR1 target gene) were elevated in rFNAs from postmenopausal women with obesity." (PMID 34485137, 2021).
ovarian carcinoma (2 papers, 2022). A malignant neoplasm originating from the surface ovarian epithelium. "TFF1, which is decreased by chemical fumes, is a protective factor against ovarian cancer." (PMID 35602164, 2022). "Despite displaying distinct protein expression patterns in ovarian carcinoma, Pearson correlation analysis revealed recurrent co-expression between TFF1/TFF2 and TFF1/TFF3." (PMID 36818673, 2022). "Elevated expression levels of TFF1 and TFF3 have been shown to correlate with changes in Ca125 (progression) and endocrine therapy response rates in ovarian cancer." (PMID 36818673, 2022). "Therefore, the TFF1 and TFF3 biomarkers may provide healthcare professionals with tools to better subclassify OC by histotype, more efficiently predict patient clinical outcome, and improve the treatment decision-making process for ovarian cancer." (PMID 36818673, 2022).
abdominal aortic aneurysm (1 paper, 2024). Enlargement and ballooning of the vessel that supplies arterial blood to the abdomen, pelvis and legs. "have shown that aorta Tregs also express Tff1 in elastase- or calcium phosphate-induced abdominal aortic aneurysms (AAA)." (PMID 39286257, 2024).
allergic rhinitis (1 paper, 2019). Inflammation of the nasal mucous membranes caused by an IgE-mediated response to external allergens. "In the allergic rhinitis murine model occurs a transdifferentiation of Clara cell with a concomitant expression of the trefoil factor family peptide 1 (TFF1) goblet cell marker in some airway regions." (PMID 31170201, 2019).
Allergy (1 paper, 2019). An allergy is an immune response or reaction to substances that are usually not harmful. "In this study, we have investigated (a) expression levels of TFF1 and TFF3, (b) tissue localization of the corresponding TFF peptides, and (c) the effects of bacterial colonization or infection and the presence of allergy on the target gene expression in sinonasal tissue from CRSwNP patients." (PMID 31683988, 2019).
aortic aneurysm (1 paper, 2022). A ruptured aneurysm located in the wall of the proximal portion of the descending aorta proceeding from the arch of the aorta. "In addition, we detected the expression of Tff1 on Tregs by using immunofluorescence, and confirmed that Tff1 could be produced by Tregs in aortic aneurysm." (PMID 35332699, 2022).
bile reflux (1 paper, 2025). "Furthermore, abnormal bile acid metabolism, particularly in bile reflux (e.g., deoxycholic acid), impairs gastric mucosal repair by inhibiting the FXR receptor and downregulating tight junction protein and TFF1 expression." (PMID 41282630, 2025).
celiac disease (1 paper, 2024). An autoimmune genetic disorder with an unknown pattern of inheritance that primarily affects the digestive tract. "These metabolites and the capsular component increased the level of expression of genes coding for mucins, trefoil factor 1 (TFF1) and claudin 18 (CLDN18) that were found to be expressed at a lower rate in celiac disease organoids." (PMID 38396767, 2024).
cervical cancer (1 paper, 2022). A primary or metastatic malignant neoplasm involving the cervix. "In the present study, the immune subtype-relevant signature (covering TMEM125, TFF1, DECR2, LONRF3, DAPL1, and ANKRD35) was quantified, which predicted cervical cancer recurrence accurately and independently." (PMID 36313466, 2022).
cholangiocarcinoma (1 paper, 2021). A carcinoma that arises from the intrahepatic biliary tree (intrahepatic cholangiocarcinoma) or from the junction, or adjacent to the junction, of the right and left hepatic ducts (hilar cholangiocarcinoma). "Hepatic TFF1 expression is increased in patients with hepatectomy, hepatolithiasis, cholangiocarcinoma, and HCC." (PMID 34146542, 2021).
chronic rhinosinusitis (1 paper, 2019). Chronic form of sinusitis. "We have detected differential expression of TFF1 and TFF3 genes and peptides in sinonasal mucosa of patients with CRSwNP, where they could play an important role in mucosal defense from bacterial infection and the development of chronic rhinosinusitis." (PMID 31683988, 2019).
co-infection (1 paper, 2025). "Moreover, the biomarkers of glandular intrinsic components (TFF1) and tumor-associated genes (VIL1 and Lgr5) were significantly upregulated, providing further evidence that host aberrations and tumor progression are triggered by co-infection of EBV with H. pylori." (PMID 40833108, 2025). "Consistently, the results showed that NGOs displayed a significant upregulation of TFF1, VIL1, and Lgr5 at 24 h after co-infection of H. pylori with EBV and a downregulation of CD44 and Axin 2 compared to the H. pylori or EBV-alone groups." (PMID 40833108, 2025). "We found that the co-infection of H. pylori and EBV induced a significant structural change and upregulated the expression of TFF1, VIL1, and Lgr5 to promote cell proliferation and tissue morphogenesis." (PMID 40833108, 2025).
cystic fibrosis (1 paper, 2022). Autosomal recessive disorder caused by pathogenic variants in the CFTR gene (cystic fibrosis transmembrane conductance regulator), which encodes a chloride and bicarbonate channel expressed in epithelial cells, and follow the diagnosis criteria. "Furthermore, in cystic fibrosis airways, TFF3 synthesis increased in surface goblet cells, whereas the elevated expression of TFF1 and TFF2 occurred in mucous cells of submucosal glands." (PMID 36499686, 2022).
endometrial adenocarcinoma (1 paper, 2022). "DSCAM-AS1 levels were found to be considerably associated with ESR1 expression (rho = 0.40, p = 8.9 × 10−8) and with ERα target gene TFF1 (PS2) (rho = 0.41, p = 2.6 × 10−8) in endometrial adenocarcinoma tissues." (PMID 35885035, 2022).
esophageal tumor (1 paper, 2017). "Finally, a significant inverse correlation between TFF1 expression and promoter methylation was observed for esophageal tumor samples (r = − 0.6999, p < 0.0001)." (PMID 29296124, 2017).
Gastric Metaplasia (1 paper, 2020). Intestinal metaplasia of the gastric mucosa is an intermediate precancerous gastric lesion in the gastric cancer cascade from chronic gastritis and atrophy to dysplasia and adenocarcinoma. "While in vitro experiments showed that IL-6 trans-signalling can overcome the repressive effects of trefoil factor 1 (TFF1) on IL-6 classic-signalling, gastric metaplasia induced by a hyperactive gp130 variant was not abrogated by a dimerised form of soluble gp130 (sgp130Fc)." (PMID 32698506, 2020).